TLR2 (toll like receptor 2)
Diseases named in the same sentence as TLR2 in open-access papers (continued):
Sharing a sentence is not in itself a finding about the gene and the disease.
bladder cancer (23 papers, 2011 to 2025). "Studies indicate that variant alleles of TLR2 (ID+DD) are associated with disease susceptibility and risk of progression in bladder cancer." (PMID 38542078, 2024). "The enhanced antitumor effects of BCG in bladder cancer cells are associated with the inhibition of TLR2-medated MEK pathway." (PMID 28881802, 2017). "In this context, SMP-105 TLR2 agonist has been proposed as an agent for the treatment of bladder cancer and TAK-242 TLR4 antagonist has been shown to exhibit antitumor effect." (PMID 41295183, 2025). "Currently, it has been approved as a TLR2/4 mixed agonist for bladder cancer and superficial bladder cancer treatment." (PMID 35745800, 2022). "BCG-infected bladder cancer cells were more prone to induction of AMP release following TLR2 activation via ERK and c-Jun pathway mediators." (PMID 28881802, 2017). "Interestingly, the Bacillus Calmette–Guerin vaccine is approved for the treatment of bladder cancer, where stimulation of TLR2 and TLR4 are responsible for the observed anti-cancer effect." (PMID 38256021, 2024). "In bladder cancer, TLR2 and TLR4 would be activated by the cell wall component of M. tuberculosis, further inducing the inflammatory responses and laying the theoretical foundation for the anti-cancer effect of BCG intravesical instillation therapy in bladder cancer." (PMID 36131933, 2022). "Previously, these BCG-derived products (BCG-CWS or BCG-derived DNA/RNA) were found to induce apoptosis in bladder cancer cells by activating TLR2, TLR4, TLR7, and TLR9 and thus inducing the myeloid differentiation primary response gene 88 (MYD88) pathway of extrinsic apoptosis." (PMID 36248858, 2022). "Additionally, TLR2/TLR4 agonists are used to treat bladder cancer." (PMID 39451226, 2024). "In addition, TLR2 has recently been suggested to be involved in bladder cancer." (PMID 24223213, 2013). "For more than thirty years, bladder cancer has been treated with Bacillus Calmette–Guérin (BCG), the TLR2/TLR4 agonist that is the most effective TLR ligand in cancer therapy." (PMID 40143078, 2025). "The TLR2/TLR4 agonist (Bacillus Calmette and Guérin) is the most effective TLR ligand in cancer therapy; it has been used to treat bladder cancer for more than thirty years." (PMID 39770406, 2024). "TLR agonists such as Bacillus Calmette-Guérin (BCG), which targets TLR2 and TLR4, were among the first approved ligands used in cancer treatment, particularly in bladder cancer." (PMID 39451226, 2024). "Recently, imiquimod and TMX-202 (TLR7 agonists) were tested for bladder cancer immunotherapy, while CpG ODN (a TLR9 agonist) and HP-NAP (a TLR2 agonist) demonstrated reduced tumor growth in an MB49 bladder cancer mouse model." (PMID 38542078, 2024). "Synergistic immune activation with two chemical molecules: Poly(I:C)—a TLR3 targeted agent—and TLR2/4 inducer-BCG led to tumor suppression and the generation of a long-lasting protective immunity in the MBT-2 murine high-grade bladder cancer model." (PMID 35745800, 2022). "In TNF-α-treated ADSCs cultured with the bladder cancer (BC) cell medium, the results showed that apoptosis ratio and OCT-4 and TLR2 genes which maintained the self-renewal ability of stem cells were decreased." (PMID 33924332, 2021). "In vivo, P-MAPA also increased the expression of TLR2 in macrophages from Leishmania chagasi-infected dogs, and of TLR2 and TLR4 in urothelial cells from female rats treated for bladder cancer." (PMID 33299378, 2020). "In bladder cancer, intravesical P-MAPA immunotherapy promoted a distinct activation of the TLR2- and TLR4-mediated innate immune system, resulting in increased IFN-γ signaling (TRIF-dependent pathway), which was more effective in the treatment of this tumor." (PMID 29343281, 2018). "Further analyses indicated an essential role of TLR2 for binding of c-Jun, p65, and Pol II to AMP promoters in BCG-infected bladder cancer cells." (PMID 28881802, 2017).
bladder cancer (continued). "Buytaert and colleagues recently investigated the transcriptional changes in bladder cancer cells upon hypericin-mediated low-dose PDT and observed upregulation of the granulocyte-macrophage colony-stimulating factor (CSF2) and TLR2 genes besides IL8." (PMID 21738796, 2011). "In addition, HPP was recognized by Toll-like receptor 2 (TLR2) and activated the signaling pathways of NF-κB and NLRP3 in a bladder cancer microenvironment model, indicating that HPP could enhance host immune system function." (PMID 32850623, 2020).
HCMV infection (23 papers, 2007 to 2024). "In line with this, the same group also found association of TLR9 variants (T/C, rs187084; C/T, rs352140) with CMV disease in children and of TLR2 (A>G, rs5743708) with increased risk of congenital HCMV infection in Polish fetuses and neonates." (PMID 36016941, 2022). "The specific SNPs at the TLR-2 genes were associated with the intrauterine transmission of CMV in Israeli pregnant women with primary CMV infection, but only when the onset of infection was limited to the second trimester of pregnancy." (PMID 34578364, 2021). "TLR2 protein levels decrease in the late stage of HCMV infection, and this is associated with the accumulation of miR-UL112-3p in fibroblasts and mononuclear THP1 cells." (PMID 33298111, 2020). "The TLR2 Arg753Gln and T597C polymorphisms are related to Gram-positive septic shock, S. aureus and cytomegalovirus infections, as well as pulmonary and meningeal tuberculosis." (PMID 30692998, 2018). "It was previously demonstrated that the TLR9–1486 and 2848 polymorphisms as well as the TLR2 1350 SNP are associated with an enhanced risk of HCMV infection and disease in newborns and infants." (PMID 28046022, 2017). "Taking into account genetic modifications within the TLR2 gene, previous studies also reported contribution of TLR2 2258 G>A coding non-synonymous SNP to HCMV infection, although the mutated homozygotes were found in some studied populations only." (PMID 28118851, 2017). "In case of TLR2 + 1350 T > C polymorphic site, the CC genotype (homozygotic status with two minor C alleles) was correlated with congenital HCMV infection." (PMID 28340580, 2017). "Regarding presented data, the age-dependent type of the involvement of TLR2 2258 G > A polymorphism to HCMV infection seems to be quite possible." (PMID 28340580, 2017). "Taking into account genetic modifications, the single nucleotide polymorphisms (SNPs) located within TLR2 gene, were reported to be correlated with HCMV infections as well." (PMID 28118851, 2017). "Among various TLR2, TLR4 and TLR9 polymorphisms, TLR2 2258 G>A SNP seems to be an important factor associated with increased risk of congenital HCMV infection in Polish fetuses and neonates." (PMID 28118851, 2017). "Likewise, TLR9 variants (T/C, rs187084; C/T, rs352140) are associated with CMV disease in children and TLR2 variants (A>G, rs5743708) are associated with increased risk of congenital HCMV infection in a Polish cohort." (PMID 36016941, 2022). "Two TLR2 SNPs (rs3804100: T > C and rs1898830: A > G) have been shown in Japanese infants to have some association with congenital CMV infection, while the TLR2 SNP (rs3804100 GG genotype) has shown a protection against intrauterine transmission of HCMV in an Israeli cohort." (PMID 34578364, 2021). "However, in case of congenital HCMV infection, GA heterozygotic status and A allele within TLR2 2258 G > A, as well as CC genotype in the other TLR2 + 1350 T > C SNP, was reported to be correlated with the infection." (PMID 28340580, 2017). "The GA heterozygotic status in the polymorphic region was correlated with HCMV infection, increasing 10 times the risk of the infection and the A allele in TLR2 SNP was significantly more frequently found among the infected fetuses and neonates than in the uninfected controls." (PMID 28118851, 2017). "In a cohort of liver transplant recipients treated at the Mayo Clinic, Minnesota, United States, some relationship was determined between homozygosity in the analyzed TLR2 polymorphism and HCMV infection, especially in tissue-invasive disease." (PMID 28118851, 2017). "However, further studies would be justified to investigate in more detail the molecular mechanism which underlies TLR2 polymorphism involvement in the development of congenital HCMV infection." (PMID 28118851, 2017).
HCMV infection (continued). "Given this context, TLR-2 protein expression was reduced by HCMV infection of normal human dermal fibroblasts (NHDFs) and THP-1 monocytic cells, demonstrating a direct correlation and with an increased accumulation of miR-UL112-3p." (PMID 37896804, 2023). "The role of TLR SNPs in congenital and acquired HCMV infection was reported for TLR2, TLR3, TLR4, TLR7, and TLR9 SNPs in various populations." (PMID 34578364, 2021). "Compton and co-workers initially identified TLR2 as a cellular factor that mediates the innate immune response to human cytomegalovirus (HCMV) infection and demonstrated that HCMV gB plays a role in activating TLR2 in permissive human fibroblast cells." (PMID 31487910, 2019). "Complex AA variants for both TLR2 2258 and TLR9 2848 G>A polymorphisms, were estimated to be at increased risk of congenital HCMV infection (OR 11.58, 95% CI 1.19–112.59; P ≤ 0.050)." (PMID 28118851, 2017). "Fifty-nine cases of HCMV infection and part of uninfected subjects has been described previously in detail for TLR2, TLR4, and TLR9 SNPs." (PMID 28046022, 2017). "The majority of the children in this study were also involved in earlier studies on the relationship between polymorphisms in the TLR2, TLR4, and TLR9 genes and HCMV infection." (PMID 28046022, 2017). "Evaluation of the role of single nucleotide polymorphisms (SNPs), located within TLR2, TLR4 and TLR9 genes, in the development of human cytomegalovirus (HCMV) infection in pregnant women and their fetuses and neonates, was performed." (PMID 28340580, 2017). "In human acute monocytic leukemia cell line THP1 and in foreskin fibroblast cell lines, HCMV infection induces the expression of TLR2, TLR3 and TLR9 genes." (PMID 28118851, 2017). "In ectocervical tissue, HCMV infection was blocked by ligands for TLR2 (LTA), as well as TLR9 (CpG) molecules." (PMID 28118851, 2017). "So far, no study has shown any relationship between genetic alterations in TLR2 2258 G>A SNP and congenital HCMV infection." (PMID 28118851, 2017). "In previous studies, Toll-like receptor 2 (TLR2) has been reported to be critical in the early response to HCMV infection by recognizing the viral surface glycoproteins gB and gH." (PMID 29194430, 2017). "What is more, a significant role in the occurrence of HCMV infection was previously confirmed for TLR2 and TLR4 molecules as well." (PMID 28340580, 2017). "On the other hand, SNPs rs3804100 and rs1898830 in TLR2 were observed at a higher frequency in Japanese infants with congenital CMV infection." (PMID 27586547, 2016). "TLR2 Arg753Gln (rs5743708) and TLR4 Asp299Gly (rs4986790) are correlated with a higher risk of acquiring CMV infection and disease in transplant patients." (PMID 27586547, 2016). "Results showed that the CC genotype of TLR2 rs3804100 and the AA genotype of TLR2 rs1898830 were significantly more frequent in infants with congenital CMV infection than in the general population." (PMID 27586547, 2016). "Polymorphisms of the TLR2 (rs3804100, rs1898830), TLR4 (rs4986791), and TLR9 (rs352140) were shown to have a role in congenital CMV infection." (PMID 27586547, 2016). "We next found that TLR2 protein level decreases at late times during HCMV infection and correlates with miR-UL112-3p accumulation in fibroblasts and monocytic THP1 cells." (PMID 25955717, 2015). "In this paper we show that miR-UL112-3p efficiently targets TLR2 during HCMV infection, resulting in the inhibition of TLR2-mediated NFκB signaling." (PMID 25955717, 2015). "These experiments revealed that, in an in vitro setting, cells become permanently unresponsive to any TLR2 stimulation in a matter of hours after HCMV infection." (PMID 25955717, 2015). "In this work we identified TLR2, a cell surface receptor that plays an important role in the detection and control of CMV infection, as a novel target of miR-UL112-3p." (PMID 25955717, 2015).
HCMV infection (continued). "Correlating with these in vitro studies, the biological importance of TLR2 to control CMV infection has been demonstrated in vivo in both human and mice." (PMID 25955717, 2015). "HCMV infection has also been found to trigger apoptosis in a TLR2-dependent manner: during congenital HCMV infection, placentae obtained from newborns often display chronic villitis and disruptions of the syncytiotrophoblast (ST)." (PMID 25955717, 2015). "Taken together, these findings indicate that TLR2 plays a crucial role in the detection and control of CMV infection in vivo." (PMID 25955717, 2015). "Taken together, these results show that TLR2 is down-regulated late during HCMV infection at time when miR-UL112-3p accumulates significantly." (PMID 25955717, 2015). "TLR2, Lyn kinase and the p35 subunit of IL-12 were all upregulated within 10 min of HCMV infection in THP-1 monocytes." (PMID 23061052, 2012). "Pre-treatment of UV-inactivated CMV particles with antibodies against gB and gH prior to infection of human fibroblasts resulted in a 40–50% reduction in secreted IL-6, confirming the importance of the recognition of gB and gH by TLR2 during CMV infection." (PMID 23061052, 2012). "Recently, HCMV infection has been shown to result in upregulation of TLR2, TLR3, and TLR9 in monocytes in the presence of the human monocyte scavenger receptor A type 1 (SR-A1)." (PMID 23061052, 2012). "The envelope glycoproteins gB and gH also interact with TLR2, and neutralizing antibodies against TLR2, gB, and gH inhibit inflammatory cytokine responses to HCMV infection in permissive human fibroblasts." (PMID 22701276, 2012). "Therefore, the common contribution of TLR9 2848 G>A, together with TLR2 2258 G>A SNP, to the occurrence of HCMV infection seems possible." (PMID 28118851, 2017). "The research was aimed to estimate the role of three single nucleotide polymorphisms (SNPs) located in TLR2 gene, and the common contribution of TLR2, and previously studied TLR4 and TLR9 SNPs, to the occurrence of congenital HCMV infection in fetuses and newborns." (PMID 28118851, 2017). "Moreover, complex AA variants for both TLR2 2258 and TLR9 2848 G > A polymorphisms, were found to be associated with an increased risk of congenital HCMV infection." (PMID 28340580, 2017). "Associations between TLR2, TLR4, and TLR9 polymorphisms with HCMV infection have been found." (PMID 28046022, 2017). "To test this hypothesis, we first monitored the protein level of endogenous TLR2 during HCMV infection in productively infected fibroblasts by western blot (IB)." (PMID 25955717, 2015). "However, recent work showing that TLR2 plays an important role in the control of CMV infection argues against this possibility." (PMID 25955717, 2015). "Such paracrine down-regulation of TLR2 could curtail the initial steps of innate signaling and antiviral defense triggered by HCMV gB and gH binding to TLR2, facilitating HCMV infection of neighboring cells and blunting activation of NK cells." (PMID 25955717, 2015). "This suggests that TLR ligands may enhance HCMV infection in vivo since GC, T. vaginalis and BV all have TLR ligands (TLR2, TLR4 and TLR2 respectively) associated with their infections." (PMID 18053251, 2007). "Thus, our data suggest that initial induction of XO upon HCMV infection contributes to peroxynitrite production, and activation of TLR2 may contribute to this process." (PMID 38953361, 2024). "The results of our study demonstrate that TLR2 2258 G>A SNP may be an important genetic factor of the previously analyzed TLR2, TLR4 and TLR9 polymorphisms, which is involved in the development of congenital HCMV infection in Polish fetuses and neonates." (PMID 28118851, 2017). "Interestingly, an association was observed in adults, where wild-type TLR2 Arg677Trp SNP showed an increased risk and heterozygote TLR2 Arg677Trp (no reported rs identifier) a decreased risk of CMV infection." (PMID 27586547, 2016).